UCP1 (uncoupling protein 1)
Diseases named in the same sentence as UCP1 in open-access papers (continued):
Sharing a sentence is not in itself a finding about the gene and the disease.
Obesity (continued). "Our results show that BS21 reduces obesity and hyperlipidemia induced by an HFD via increasing thermogenesis and exergy expenditure by UCP1." (PMID 35276805, 2022). "LCA and other TGR5 agonists that increase Ucp1 expression in BAT and enhance energy expenditure is a potential strategy for preventing obesity." (PMID 35440584, 2022). "For PCOS-related obesity, EA activated BAT sympathetic innervation and promoted the expression and coexistence of UCP1 to increase the high-energy regions, while EA had anti-inflammatory effects in WAT." (PMID 35436959, 2022). "Obesity and metabolism-related genotypes were also assessed by 10 studies, including FTO, UCP1, MC4R, and ADIPOQ." (PMID 36235756, 2022). "Evaluated genotypes also included those relating to cardiovascular health (ACE), obesity and metabolism-related genotypes (FTO, UCP1, MC4R, and ADIPOQ), sweet taste perception (Tas1R2 and KCTD10), and endurance (GDF5)." (PMID 36235756, 2022). "Consistently, GPR30 deficiency enhances beige adipocyte differentiation in white adipose tissue (WAT) and activates the thermogenic browning of subcutaneous WAT due to up-regulation of UCP-1, which thereby protects female mice from HFD-induced obesity." (PMID 35592783, 2022). "Collectively, the SIRT1-PGC-1α-UCP1 axis explains the GABA and FCLL-GABA induced anti-obesity mechanism." (PMID 35458241, 2022). "The non-12 hydroxylated bile acids resist the obesity phenotype in mice through TGR5-mediated activation of brown adipose tissue (BAT) and upregulation of uncoupling protein 1 (UCP1) expression." (PMID 36386219, 2022). "Yet, in light of pandemics of obesity and the metabolic syndrome, much attention is focused on the ability of BAT to dissipate energy in form of heat through uncoupling protein-1 (UCP1)–mediated mitochondrial uncoupling." (PMID 33257475, 2021). "At least in mice, induction of UCP1 by treatment with a β3-adrenaergic agonist increases both BAT thermogenesis and whole-body oxygen consumption, preventing the development of obesity." (PMID 33676029, 2021). "Consistently, SHQA treatment increased UCP1 protein levels, suggesting that SHQA-induced thermogenic signaling in WAT contributes to its anti-obesity effect." (PMID 34716371, 2021). "A recent report revealed that silk peptide prevents HFD-induced obesity and induces WAT browning by activating AMPK and increasing UCP1 expression in mice." (PMID 34646848, 2021). "WAT mainly stores energy and is increased in obesity, whereas BAT dissipates energy via specific expression of Ucp1." (PMID 33462408, 2021). "Studies indicated that PPARα activated UCP1 and promoted the expressions of the genes related to thermogenesis to repress HFD-induced obesity." (PMID 34174964, 2021). "Likewise, BAT has high levels of uncoupling protein 1 (UCP1), which confer thermogenic properties by uncoupling between respiration and ATP synthesis during the FA oxidation in adipocytes; hence, UCP1 is recently considered as a potential therapeutic target against obesity." (PMID 34603210, 2021). "We also investigated the involvement of UCP1-independent thermogenic pathways, including the creatine cycling and calcium futile cycle, as well as BAT-secreted batokines in regulating obesity-prone phenotypes in D1KO mice." (PMID 34824202, 2021). "In animal models of obesity, upregulation of FNDC5 increased uncoupling protein 1 (UCP1) expression and oxygen consumption, leading to high energy expenditure." (PMID 33817324, 2021). "The major SCFAs reduce lipogenesis and increase fatty acid oxidation, thermogenesis, and adipocyte browning in adipose tissue, muscle, and liver by increasing the expression of PGC1α, UCP1, and AMPK activation, which appear to have anti-obesity effects." (PMID 34884471, 2021). "Surprisingly, some of our newest data highlight mild cold-induced endogenous FGF21 as the primary metabolic regulator of obesity resistance, possibly mediated via WAT browning in UCP1-KO mice." (PMID 32714278, 2020).
Obesity (continued). "Rcan1-null mice also had increased expression of uncoupling protein 1 (UCP-1) in adipose tissue, which is a mitochondrial uncoupler well-known to have implications for diet-induced obesity." (PMID 32033037, 2020). "Uncoupling protein 1 (UCP1) executes thermogenesis in brown adipose tissue, which is a major focus of human obesity research." (PMID 32005798, 2020). "Our findings reveal the ability of UP to reduce the occurrence of obesity through increased browning of white adipose tissue via increased AMPKα, PPARγ, PGC-1α, and UCP-1 expression." (PMID 33425000, 2020). "This study was performed to evaluate anti-obesity potential of Commiphora myrrha resin ethanolic extract (CME) with the respect to expression of leptin, adiponectin and uncoupling protein 1 (UCP1) in rats." (PMID 32197395, 2020). "An ectopic expression of UCP1 in WAT is induced by β3-agonists and results in resistance to HFD-induced obesity." (PMID 33339214, 2020). "The data also suggest a metabolic link between increased energy expenditure through UCP-1 overexpression in WAT and demonstrates the anti-obesity efficacy of LI85008F in HFD fed obese rats." (PMID 32859217, 2020). "Recent evidence indicates that the anti-obesity and anti-diabetic activities of FGF21 are UCP1-independent." (PMID 32849287, 2020). "Thus, compounds inducing UCP1 in WAT may be useful therapeutic agents for the treatment of obesity." (PMID 33339214, 2020). "While mild cold exposure is essential to trigger FGF21 release in UCP1-KO mice, FGF21 only unfolds its anti-obesity effect in combination with overnutrition in the form of high-fat diets." (PMID 32714278, 2020). "This protein, by suppressing UCP1, increases mitochondrial coupling, and its knockout leads to higher metabolic rate, increased lipolysis in BAT, and resistance to diet-induced obesity and diabetes." (PMID 32872317, 2020). "Ucp1 mRNA was decreased to 60% in NOD1 mice on HFD, which agrees with the observed obesity under HFD in NOD1 KO mice." (PMID 32704052, 2020). "Initial studies, where brown adipocytes were genetically ablated with a toxin driven by the UCP1 promoter, demonstrated for the first time the protective effect of BAT against obesity and T2D." (PMID 32012991, 2020). "Brown adipose tissue (BAT) dissipates energy through the activation of uncoupling protein 1 (UCP-1) found in mitochondria and converts fat through thermogenesis to defend against obesity." (PMID 33042284, 2020). "In animal models of obesity, the addition of RSV to a high-fat diet-induced UCP1 expression and oxygen consumption in BAT, resulting in the increased basic metabolic rate and, in this way, successfully counteracted accumulation of AT." (PMID 32872317, 2020). "In previous researches, EA can prevent obesity to induce the expression of PGC-1α both in WAT and BAT, and UCP1 expression is also remarkably elevated by EA." (PMID 33551999, 2020). "Skeletal muscle-specific UCP1 transgenic (HSA-UCP1-Tg) mice exhibit a healthy aging phenotype, such as decreased atherosclerosis and obesity and prolonged life span." (PMID 32079324, 2020). "In mice, obesity and its metabolic comorbidities can be reversed by the transplantation of BAT or ASCs that can form UCP1-expressing adipocytes in vivo." (PMID 33114405, 2020). "EGR1 directs tendon differentiation, promotes tendon repair and blocks energy expenditure via direct uncoupling protein 1 (UCP1) transcription repression and counteracts obesity." (PMID 33613572, 2020). "UCP1, being the ultimate marker of BAT, is of interest for the genetics of obesity and the focus of this review." (PMID 32450815, 2020). "These processes were correlated with the increased gene expression of Dio2 and Ucp-1, which represents brown adipose tissue (BAT) activation, in both WD-induced atherosclerosis and high-fat-induced obesity models." (PMID 31570705, 2019).
Obesity (continued). "However, although this obesity-promoting effect of UCP1 ablation has been reported from different laboratories, a serious limitation of the existing studies has been that the study object has been restricted to a single mouse strain: the notoriously obesity-prone C57Bl/6 mouse." (PMID 30807213, 2019). "In the current experiment, the thermogenesis of mice was increased after FST injection, and the expression of the Ucp1 gene in beige fat was increased, indicating that FST resists obesity by promoting energy metabolism in beige fat." (PMID 31365569, 2019). "Understanding the regulation mechanism of UCP1/UCP3 and their exact role within the mitochondria inner membrane will provide new strategies to treat obesity and its related diseases." (PMID 31806023, 2019). "Our results highlight pronounced age-dependent differences in the expression of UCP1 and UCP3 that is especially important in the pathogenesis of obesity, diabetes, and cardiovascular diseases." (PMID 31806023, 2019). "Thus, the effect of UCP1 ablation on obesity may be limited to this very special strain." (PMID 30807213, 2019). "Energy may be dissipated to the environment in the form of heat via UCP1, which uncouples oxidative phosphorylation in the inner mitochondrial membrane present in brown and brown-like adipocytes, and increased expression and activity of UCP1 protects against diet-induced obesity." (PMID 31126082, 2019). "UCP1 is abundantly expressed in the mitochondria of mammalian BAT, and can burn chemical fuels by uncoupling cellular respiration to defend against obesity." (PMID 31365569, 2019). "In the present study, we analyze different populations of patients with severe obesity (PWO), with the aim of identifying new determinants of REE including UCP1 expression in abdominal SAT and VAT." (PMID 31440209, 2019). "The isoflavone-rich fraction of the Kudzu (Puerariae thomsonii) flower exerted anti-obesity effects by increasing lipolysis in WAT and Ucp1 expression in the BAT of mice with HFD-induced obesity." (PMID 30149637, 2018). "Alterations in BAT thermogenesis were confirmed by elevated and decreased Uncoupling Protein 1 (Ucp1) and ELOVL Fatty Acid Elongase 3 (Elovl3) mRNA expression during cold or diet-induced obesity (DIO), respectively." (PMID 30190464, 2018). "First, one of the key roles of thyroid hormone is to up-regulate UCP1 expression in BAT to increase adaptive thermogenesis and counteract obesity, which overlaps with the action of GDF15." (PMID 30687235, 2018). "This is in part due to the overwhelming evidence that activation of β3-ARs leading to increased UCP1 expression and function in BAT can reverse obesity, and prevent the development of insulin resistance and diabetes in rodents." (PMID 29910772, 2018). "The adipose‐specific transgenic expression of UCP‐1 prevents obesity in mice 74, whilst the genetic ablation of BAT in mice results in obesity." (PMID 26227946, 2016). "Therefore, although “metabolically healthy” obesity phenotype supposedly could be characterized by higher brown fat contents, UCP1 in this case looks rather like a marker of more “problastomogenic” visceral fat tissue, for which the omentum serves as one of depots." (PMID 27853670, 2016). "SIRT 1 is an essential regulator of systemic energy homeostasis and plays an important therapeutic role in the treatment of obesity and MetS by inducing brown-like adipocyte formation in WAT and by increasing mRNA and/or protein expression of UCP1." (PMID 27399675, 2016). "Uncoupling protein 1, UCP2 and UCP3 are candidate genes for obesity because they decrease mitochondrial membrane potential and mediate proton leak." (PMID 24804925, 2014).
Obesity (continued). "TNFα has been reported to induce brown adipocytes apoptosis in primary culture, inhibit UCP-1 expression and mediate BAT atrophy in insulin resistance syndromes such as obesity and diabetes." (PMID 25144367, 2014). "Nevertheless, differences between rodents and humans in terms of regulation of UCP1 expression are highly relevant, as modulation of BAT activity and browning of WAT are being considered as potential anti-obesity targets." (PMID 24059847, 2013). "Because of UCP1, which dissipates caloric energy as heat, BAT has an important role in preventing obesity, as shown in our earlier study using UCP1-knockout mice." (PMID 24391749, 2013). "To examine a role of activation of BAT thermogenesis in the anti-obesity effect of BOF, we examined the mRNA expression of the thermogenesis factor, UCP-1, in BAT and rectal temperatures in KKAy mice at the age of 17 weeks." (PMID 24130717, 2013). "Uncoupling protein 1, UCP2 and UCP3 are regarded as candidate genes for obesity and T2DM because they have been found to decrease mitochondrial membrane potential and mediate proton leak." (PMID 23365654, 2013). "This was proved by a study that showed lowered activation of sympathetic nerve and declined expression of UCP-1 in BAT of obese rats and by another in vivo study that reported overexpression of UCP-1 reduced degree of obesity induced by high fat diet." (PMID 23043591, 2012). "Evo was found to mimic the capsaicin-like anti-obese activities; however, in uncoupling protein-1 (UCP1)-knockout mice, Evo triggered a UCP1-independent mechanism to prevent diet-induced obesity." (PMID 21320305, 2011). "Here, we demonstrate that COX activity is crucially involved in the induction of UCP1 expression in WAT providing further evidence for a role of COXs in the control of energy balance and obesity development." (PMID 20613988, 2010). "In energy allocation, cAMP-driven browning dissipates WAT energy as heat to resist diet-induced obesity; activated brown adipose tissue (BAT) uses uncoupling protein 1 (UCP1) to transport fatty acids into mitochondria for heat production, forming a ‘lipolysis – thermogenesis’ axis." (PMID 41503874, 2026). "Cold exposure induces genes of both fatty acid synthesis and oxidation in BAT205–207 while WAT also shows cold-induced FFA/TG cycling (without UCP1 involvement), more pronounced in obesity-resistant A/J than in B6 mice." (PMID 40983641, 2025). "UCP1 expression was significantly reduced in the CON compared to the NC group (p < 0.05), indicating a reduction in thermogenic capacity due to HFD-induced obesity." (PMID 40508039, 2025). "In summary, the current study demonstrates LETMD1 as a pivotal player in enhancing non-canonical, UCP1-independent energy expenditure in human beige adipocytes, and therefore establishes it as a druggable target for obesity and metabolic diseases." (PMID 39897567, 2025). "Accordingly, the impairment of β3-adrenergic induction of UCP1 expression in WAT may explain the higher TG level and the more severe high-fat diet-induced obesity in Epac1-/- mice." (PMID 40411181, 2025). "Of particular interest is beige adipose tissue, which, through the expression of uncoupling protein 1 (UCP1), expends energy in the form of thermogenesis and may play a protective role against obesity and insulin resistance." (PMID 41262738, 2025). "Of clinical significance, we also found that both mRNA and protein levels of FBXW7 were increased in subcutaneous WAT of obese human, and was negatively correlated with Ucp1 levels, suggesting FBXW7 is involved in the suppression of thermogenic functions and the development of obesity." (PMID 39747664, 2025). "Its ability to inhibit obesity by increasing the expression of pPKA and its downstream lipolytic proteins, increasing the expression of UCP1 proteins, and increasing the browning of white fat has not been reported." (PMID 40332049, 2025).
Obesity (continued). "Similarly, obesity leads to hypertrophic adipocytes and inflammation, and in mouse models of aged, diet-induced obesity, there is a significant reduction in BAT UCP1 levels and thermogenic gene expression." (PMID 40855678, 2025). "Additionally, arctiin, a plant-derived lignan, increases uncoupling protein 1 (UCP1) expression in WAT and promotes thermogenesis through adenosine A2A receptor activation, demonstrating anti-obesity efficacy via browning." (PMID 41471332, 2025). "Using a 24-week high-AGE diet murine model, we integrate metabolomics, molecular profiling, and functional assays to identify Myr’s efficacy in reversing obesity and metabolic disorders and elucidate the AMPK-PGC1α-UCP1 cascade as the central mechanism driving these benefits." (PMID 40362857, 2025). "Our data indicate for the first time that TRPV1 activation counters obesity at thermoneutrality permissive for UCP-1 and the enhancement of PRDM-16 is not beneficial in the absence of UCP-1." (PMID 39204203, 2024). "Our human adipocytes from individuals with obesity and mouse BAT cells in vitro using an earlier analogue (FG2216) closely related to roxadustat (FG4592) showed induction of β3-adrenergic signalling and UCP1 levels." (PMID 39209825, 2024). "Thus, the transcription of UCP1 mediated by the SIRT5-C/EBPβ axis is critical in regulating energy balance and obesity-related metabolism." (PMID 39408844, 2024). "pTSL@(P+I) effectively upregulates UCP1 and COX5B expression by activating the transcription axis of PPARγ/PGC1α and HSF1/PGC1α, thereby promoting white adipose tissue browning and reducing obesity." (PMID 39195401, 2024). "In brown adipose tissue, METTL3 deletion decreases the m6A modification and expression of the PR domain containing 16 (PRDM16), uncoupling protein 1 (UCP-1), and peroxisome proliferator-activated receptor gamma (PPARG) and thereby promotes high-fat diet-induced obesity." (PMID 38560499, 2024). "Indeed, previous studies suggest that therapeutic strategies aimed at increasing UCP1 expression, using synthetic and natural bioactive compounds, could be an effective approach to promote adipocyte browning and eventually combat metabolic diseases such as obesity." (PMID 39796132, 2024). "Also, the expression of Ucp-1 in the subcutaneous white adipose tissue of DIO-R group mice was significantly higher than that of the DIO group, which can resist obesity by increasing heat production." (PMID 38732501, 2024). "The production of irisin phosphorylates p38 MAPK and activates extracellular signal-regulated kinase (ERK), thereby leading to white fat browning, increased energy expenditure, and upregulation of uncoupling protein 1 (UCP1), thus alleviating HFD-induced obesity and insulin resistance in vivo." (PMID 39250437, 2024). "UCP1 expression in BAT, but not in WAT or brown/white differentiated pre-adipocytes, was reduced with increasing age, obesity, and adverse cardiometabolic risk factors such as fasting glucose, insulin, and blood pressure." (PMID 38917410, 2024). "This nanocomplex effectively upregulates UCP1 and COX5B expression by activating the transcription axis of PPARγ/PGC1α and HSF1/PGC1α, thereby promoting white adipose tissue browning and improving obesity." (PMID 39195401, 2024). "Finally, we demonstrated in vivo that purinergic signalling drives anti-obesity effects and enhances BAT UCP1 in conditions of minimally adaptive thermogenesis requirements." (PMID 39484996, 2024). "There was thus no protection against obesity as a consequence of the large amount of UCP1, even though the mice were exposed to the thermogenesis-inducing high-fat diet." (PMID 37499977, 2023). "Moreover, recent studies have shown that increasing energy expenditure via thermogenesis involving UCP1 and AMPK is a promising strategy for combating obesity." (PMID 36839173, 2023). "Catechin and Quercetin reduced obesity by regulating lipid metabolism and stimulating non-shivering thermogenesis (Ucp1, Pgc1a)." (PMID 36839173, 2023).